LNCHR1 (lncRNA induced by HCV, regulator of SREBF1)
Gene: Long non-coding RNA gene on chromosome 12 (94,491,546 to 94,496,442, reverse strand). Ensembl gene ENSG00000257400.
Diseases named in the same sentence as LNCHR1 in open-access papers:
LNCHR1 is named in the same sentence as 5 diseases in open-access papers, as found by Europe PMC text mining. Sharing a sentence is not in itself a finding about the gene and the disease. The quoted sentences say what the papers report.
hepatoma (1 paper, 2023). "TG and LD accumulation can be inhibited by lncHR1 in both cultured hepatoma cells and in transgenic mice." (PMID 36979720, 2023).
Hypercholesterolemia (1 paper, 2025). An increased concentration of cholesterol in the blood. "A more recent study reported that RP1-13D10.2, MANTIS, and lncHR1 were overexpressed in individuals with hypercholesterolemia, and that atorvastatin treatment significantly suppressed lncHR1 expression." (PMID 40746725, 2025).
steatosis (1 paper, 2023). Increased lipid within the cytoplasm of cells. "On the other hand, LncHR1 regulate SREBP-1c levels and the phosphorylation of AKT in the steatosis cell model." (PMID 36979720, 2023).
cancer (1 paper, 2025). A tumor composed of atypical neoplastic, often pleomorphic cells that invade other tissues. "LncHR1 was shown to repress SREBP‐1c gene expression; however, lncHR1 is not liver‐specific and has very low background expression in all human tissues and cancers." (PMID 40596757, 2025).
LNCHR1 also shares sentences with these, for which no sentence is quoted: Cholestatic liver disease (1 paper).